TRAF1 (TNF receptor associated factor 1)
Diseases named in the same sentence as TRAF1 in open-access papers (continued):
Sharing a sentence is not in itself a finding about the gene and the disease.
atherosclerosis (5 papers, 2013 to 2024). A disease characterized by the build-up of fatty material and calcium deposition in the arterial wall resulting in partial or complete occlusion of the arterial lumen. "Furthermore, the rs2416804 allele in the TRAF1 gene was associated with carotid intima-media thickness, a marker for subclinical atherosclerosis that predicts subsequent clinical cardiovascular events." (PMID 35252400, 2022). "As atherosclerosis is driven by obesity and hyperlipidemia, improved metabolism in TRAF1 deficiency may contribute to its protective properties in atherosclerotic CVD, even in the light of enhanced inflammation." (PMID 35252400, 2022). "Experiments of mouse models of atherosclerosis have provided evidence that TRAF1, 5 and 6 regulate the pathogenesis of this disease." (PMID 23758787, 2013). "Up-regulated DEGs included known atherosclerosis genes such as the liver X receptor gene NR1H2, and NEXN, TRAF1, TLR7 and LGALS3BP, implicating tumor necrosis factor and toll-like receptor signaling and glycan-binding protein pathways." (PMID 37205656, 2023). "This decrease of de novo atherosclerosis in the absence of TRAF1 is accompanied by a lower content of macrophages and lipids in TRAF1-deficient plaques, an effect likely caused by reduced VCAM-1 and ICAM-1 expression on EC and reduced β1-integrin expression on macrophages." (PMID 35252400, 2022).
glioma (5 papers, 2017 to 2025). A benign or malignant brain and spinal cord tumor that arises from glial cells (astrocytes, oligodendrocytes, ependymal cells). "Promoter hypermethylation at ESR1, expression of TRAF1 and mutations in NF-kB are all known to be associated with the emergence of glioma." (PMID 28957313, 2017). "We find that in the PIN, both PBX3 and CARHSP1 are indirectly connected to each other (as well as several of their other neighbors in the CSD-network) through the intermediary of TRAF1, whose overexpression is also associated with the emergence of glioma." (PMID 28957313, 2017). "To comprehensively evaluate the prognostic significance of TRAF family members (TRAF1–7) in glioma, we first analyzed their expression patterns in The Cancer Genome Atlas (TCGA) glioma cohort." (PMID 39932808, 2025). "There have been few studies on the expression and function of TRAF1 in glioma, so the role of TRAF1 in glioma can only be inferred from its interaction function with TNFRSF12A and its cancer-promoting effect in other types of cancers." (PMID 37005685, 2023). "Notably, in COAD (OS: n = 448, p = 0.030), KIRC (OS: n = 531, p = 0.012), Brain Lower Grade Glioma (LGG) (OS: n = 524, p < 0.001), and THYM (OS: n = 118, p = 0.038), elevated expression of TRAF1 was associated with poorer patient outcomes." (PMID 38825674, 2024).
Hodgkins lymphoma (5 papers, 2015 to 2025). A heterogeneous group of malignant lymphoid neoplasms of B-cell origin characterized histologically by the presence of Hodgkin and Reed-Sternberg (HRS) cells in the vast majority of cases. "LMP1 and TRAF1 co-localize in acquired immunodeficiency syndrome (AIDS)-associated lymphoma, PTLD, and Hodgkin lymphoma samples." (PMID 25996949, 2015). "Abundant TRAF1 expression is a hallmark of multiple EBV-associated human malignancies, including Hodgkin lymphoma and post-transplant lymphoproliferative disorder." (PMID 25996949, 2015). "TRAF1 is abundantly expressed in EBV-infected immunoblasts in patients with infectious mononucleosis, and is also highly expressed in EBV-associated PTLD and Hodgkin lymphoma, where TRAF1 serves as an important biomarker." (PMID 25996949, 2015). "TRAF1 promotes Hodgkin disease Reed-Sternberg cell survival." (PMID 25996949, 2015). "TRAF1 confers resistance to apoptosis in NSCLC, Hodgkin’s lymphoma, and renal cell carcinoma, in which it specifically diminishes the sensitivity to sunitinib." (PMID 40299479, 2025). "There is high and consistent TRAF1 overexpression in EBV-induced lymphoproliferations and Hodgkin's disease." (PMID 30619326, 2018). "TRAF1 expression is ubiquitously elevated in skin squamous cell carcinoma (SSCC), non-small cell lung cancer (NSCLC), Hodgkin lymphomas (HLs) and non-Hodgkin lymphomas (NHLs)." (PMID 30294322, 2018).
juvenile idiopathic arthritis (5 papers, 2010 to 2025). Juvenile idiopathic arthritis (JIA) is the term used to describe a group of inflammatory articular disorders of unknown cause that begin before the age of 16 and last over 6 weeks. "TRAF1/C5 associated with several autoimmune diseases other than RA such as juvenile idiopathic arthritis (JIA) and systemic lupus erythomatodes." (PMID 20205706, 2010). "Other loci, including STAT4, tnf receptor associated factor 1(TRAF1)/C5, Chr6q23, kinesin family member 5A (KIF5A), and protein kinase C theta (PRKCQ)are involved in juvenile idiopathic arthritis." (PMID 40236704, 2025). "Even the TRAF1/C5 association is not unique to RA as there have been reports of association with juvenile idiopathic arthritis and systemic lupus erythematosus." (PMID 20854658, 2010).
lung carcinoma (5 papers, 2018 to 2022). "A number of mutations in the TRAF1 gene have been identified in human lung cancer and several other cancers and these are discussed elsewhere in this topic." (PMID 30619326, 2018). "Research showed overexpression of TRAF1 in human lung cancer cells, which is consistent with our analysis outcome." (PMID 35126793, 2022). "Knocking down TRAF1 expression in human lung cancer cell lines impaired phosphorylation of the oncogene serine/threonine-protein kinase, BRAF, and affected TRAF2-mediated BRAF Lys48-linked ubiquitination." (PMID 30619326, 2018). "Taken together, these findings identify TRAF1 as a therapeutic target in skin cancer, lung cancer, and T cell and B cell lymphomas." (PMID 30294322, 2018). "In this lung cancer model, TRAF1 affects TRAF2-mediated K48-linked ubiquitination and degradation of BRAF, and thereby promotes the survival and proliferation of lung cancer cells." (PMID 30294322, 2018). "TRAF1 KD led to decreased BRAF protein expression, decreased downstream MEK/ERK activation, and inhibited cell growth in human lung cancer cell lines." (PMID 34759347, 2022).
non-small cell lung carcinoma (5 papers, 2018 to 2022). A group of at least three distinct histological types of lung cancer, including non-small cell squamous cell carcinoma, adenocarcinoma, and large cell carcinoma. "Recent studies reported that high expression of TRAF1 was positively correlated with a poor prognosis in non-small cell lung cancer patients." (PMID 35194031, 2022). "Depletion of TRAF1 decreased the proliferation capacity and induced the apoptosis of non-small cell lung cancer cells." (PMID 35194031, 2022). "The upregulated antiapoptotic protein TRAF1 activates the PI3K/Akt/NF-κB signaling pathway in non-small cell lung cancer (NSCLC)." (PMID 34749775, 2021). "Two recent studies reported that TRAF1 is overexpressed in human non-small cell lung cancer and that TRAF1 expression level inversely correlated with patient survival." (PMID 30619326, 2018). "In addition recent evidence shows that human squamous cell carcinoma and non-small cell lung carcinomas can show overexpression of TRAF1." (PMID 30619326, 2018). "Besides being produced by immune cells, TRAF1 can be overexpressed by neoplastic cells in different B cell malignancies, and in solid tumors including non-small cell lung cancer for which TRAF1 has been proposed as a biomarker of tumor progression and worst clinical outcome." (PMID 34975867, 2021).
renal cell carcinoma (5 papers, 2017 to 2025). "Experimental evidence indicates that reducing TRAF1 expression can exacerbate the proliferation of renal cell carcinoma cells, diminish treatment-induced apoptosis, and increase resistance to Sunitinib, a key therapeutic agent." (PMID 38825674, 2024). "For instance, TRAF1 is found to be underexpressed in renal cell carcinoma." (PMID 38825674, 2024).
Arthritis (4 papers, 2021 to 2025). Inflammation of a joint. "We have previously shown that TRAF1 knockout mice were more susceptible to an inflammasome-driven model of MSU crystal–induced arthritis than TRAF1 wild-type (WT) littermates." (PMID 41285029, 2025). "Genetic variations in TRAF1 have been linked to an increased risk of RA, and experimental disruption of TRAF1/cIAP2 interactions has been shown to attenuate inflammation and disease severity in arthritis models." (PMID 40649852, 2025). "Remarkably, mice harboring the TRAF1 V196A mutation produced significantly lower IL-1β levels in response to a sublethal dose of LPS and exhibited reduced joint inflammation and cellular infiltration in the MSU crystal–induced arthritis model compared with TRAF1 WT littermate mice." (PMID 41285029, 2025). "Finally, we employed the MSU crystal–induced arthritis model and showed that TRAF1V196A mice exhibit significantly reduced inflammation and joint swelling compared to TRAF1 WT littermate mice." (PMID 41285029, 2025).
asthma (4 papers, 2022 to 2025). "For instance, exosomes derived from MSCs inhibit tumor necrosis factor receptor-associated factor 1 (TRAF1)-mediated macrophage polarization and promote M2 polarization, thereby modulating the inflammatory response and ameliorating severe steroid-resistant asthma." (PMID 38655063, 2024). "Intratracheal administration of hUCMSC-derived EVs ameliorated severe, steroid-resistant asthma in a mouse model by moderating inflammation, which is achieved by reshaping macrophage polarization via inhibition of TRAF1." (PMID 36466836, 2022). "Furthermore, hUCMSC-EVs ameliorated severe steroid-resistant asthma (SSRA) by modulating macrophage polarization via the TRAF1/NF-κB/PI3K/AKT axis, highlighting their broad anti-inflammatory potential." (PMID 41009408, 2025). "For example, exosomes derived from mesenchymal stem cells inhibit TRAF1 to remodel macrophage polarization and suppress M1 polarization, thereby modulating the inflammatory response and ameliorating severe steroid-resistant asthma." (PMID 38655063, 2024). "EV act on TRAF1-mediated macrophage polarization, thereby treating severe steroid-resistant asthma." (PMID 36875046, 2023).
melanoma (4 papers, 2023 to 2024). A malignant, usually aggressive tumor composed of atypical, neoplastic melanocytes. "Our results suggest that TRAF1 is a prognostic factor in melanoma." (PMID 39439891, 2024).
systemic lupus erythematosus (4 papers, 2010 to 2019). An autoimmune multi-organ disease typically associated with vasculopathy and autoantibody production. "Polymorphisms of genes involved in TNF-receptor signaling such as TNF receptor-associated factor 1 (TRAF1) have been associated with RA and other autoimmune conditions including systemic lupus erythematosus (SLE), but not with giant cell arteritis." (PMID 23125866, 2012).
viral infection (4 papers, 2015 to 2024). "In line with this, in H1N1/WSN and H5N3 virus infection an elevated level of IFIT1 was associated with increased expression of anti-apoptotic genes XIAP associated factor 1 (XAF1) in both viruses and TNF receptor-associated factor 1 (TRAF1) in H5N3 virus infection in response to early cell death." (PMID 28558796, 2017). "In summary, these siRNA silencing results confirm that TRAF1 negatively regulates virus infection and release by interacting with the MAVS protein and is involved in the RIG-I pathway." (PMID 38995016, 2024). "Interestingly, while the virion yield showed a step-by-step increase along with the infection time from the control cells, the knockdown of the endogenous TRAF1 substantially enhanced the virus infection and release." (PMID 38995016, 2024). "TRAF1 contributes to control of chronic viral infection and can limit inflammation." (PMID 30619326, 2018). "However, the relationship between RIP-1 and the TRIF/TRAF1, TRAF2, and TRAF3 pathways to produce cytokines after viral infection is unknown." (PMID 25754842, 2015). "In this study, we observed the TLR3/TRIF/RIP-1 pathway also involved in TRAF1, TRAF2 and TRAF3 activation, but not TRAF6 after stimulation by dsRNA or viral infection in the corneal epithelium." (PMID 25754842, 2015).
colon cancer (3 papers, 2017 to 2023). "TRAF1 expression is also induced in human colon cancer cells." (PMID 28842689, 2017).
gastric cancer (3 papers, 2012 to 2019). A primary or metastatic malignant neoplasm involving the stomach. "In a previous study, we found that TRAF1 was upregulated in several gastric cancer cell lines, including BGC823, SGC7901, and MGC803." (PMID 25737718, 2015). "It is possible that cagA+/vacAs1+/vacAm1+ H. pylori upregulates TRAF1 activation, which triggers 4-1BB–mediated Bcl-xL activation, thereby exerting an antiapoptotic effect and contributing to the pathogenesis of gastric cancer." (PMID 25737718, 2015). "Future studies should continue to investigate the effects of the cagA+/vacAs1+/vacAm1+ virulence genotype on TRAF1, 4-1BB, and Bcl-xL expression in cultured gastric cancer cells." (PMID 25737718, 2015). "In summary, our study implies that cagA+/vacAs1+/vacAm1+ H. pylori infection might promote gastritis progression to gastric cancer, possibly by upregulating TRAF1, 4-1BB, and Bcl-xL expression in gastric mucosal tissue." (PMID 25737718, 2015). "Previous studies have indicated that the expression of TRAF1 and TRAF2 is up-regulated in gastric cancer cells." (PMID 31835889, 2019). "Nine human RNAs were significantly upregulated in EBV-infected compared to EBV negative gastric cancers: FCER2, MS4A1 (CD20), PLUNC, TNFSF9, TRAF1, CXCL11, IFITM1, PPARG, and FCRL3.." (PMID 22929309, 2012).
gout (3 papers, 2024 to 2025). A condition characterized by painful swelling of the joints, which is caused by deposition of urate crystals. "In a more recent study, we employed a monosodium urate (MSU) crystal-induced model of gout in mice and reported that TRAF1-deficient mice exhibited a significant increase in joint swelling and inflammatory cell infiltration into the synovium compared to their wildtype littermates." (PMID 39062579, 2024). "The authors therefore suggest that this unique inhibition of inflammasome activation by TRAF1 is important for limiting the onset and progression of gout." (PMID 41446873, 2025). "Moreover, genetic knockout of TRAF1 markedly exacerbates joint inflammation and swelling in a murine gout model." (PMID 41446873, 2025). "Ultimately, selectively targeting the TRAF1/cIAP2 interaction could pave the way for novel therapeutic strategies for inflammasome-driven diseases such as gout." (PMID 41285029, 2025). "Thus, we asked whether the reduced inflammasome activation and IL-1β production observed in TRAF1 mutants that do not interact with cIAP2 could be beneficial in an inflammasome-driven disease like gout." (PMID 41285029, 2025).
small cell lung carcinoma (3 papers, 2009 to 2020). Small cell lung cancer (SCLC) is a highly aggressive malignant neoplasm, accounting for 10-15% of lung cancer cases, characterized byrapid growth, and early metastasis. "The "small cell lung cancer" KEGG pathway, which contains the TRAF1 gene, is significantly enriched with significant main effect p-values, but not with significant interaction effects." (PMID 20018077, 2009). "For example, in the Small cell lung cancer there is a long chain of regulations connecting the ECM-receptor LAMB1 and TRAF1 which is represented by a directed edge in BNKL - inhibition in the first class (red tee arrowhead) and activation in the second (blue arrowhead)." (PMID 24565081, 2013).
B-cell chronic lymphocytic leukemia (2 papers, 2018 to 2024). "For instance, elevated expression of TRAF1 is linked to the advancement of B lymphocyte malignancies, such as chronic lymphocytic leukemia (CLL), non-Hodgkin lymphoma (NHL), and Burkitt’s lymphoma." (PMID 38825674, 2024).
colitis (2 papers, 2023). Inflammation of the colon. "The AS events of Bnip2, Traf1, and Traf7 that enriched in apoptotic process in acute colitis models have been verified by PCR." (PMID 37158534, 2023). "For example, there was significant induction of Traf1, Tnfrsf9, Hif1a, Slc2a1 and Pim1 in TREG clusters in CPI colitis in comparison with TREG clusters in control mice." (PMID 37872166, 2023).
colorectal cancer (2 papers, 2021 to 2024). A primary or metastatic malignant neoplasm that affects the colon or rectum. "TRAF1, on the other hand, is targeted by miR-483, a suppressor in colorectal cancer that hampers cell proliferation and migration." (PMID 38802881, 2024). "Additionally, miR-483 has been shown to inhibit the proliferation and migration of colorectal cancer cells by targeting TRAF1." (PMID 34749775, 2021).
diffuse large B-cell lymphoma (2 papers, 2018 to 2023). "Mediastinal large B-cell lymphoma (MLBCL), a subtype of diffuse large B-cell lymphoma (DLBCL), and HL have a shared survival pathway with high levels of expression of TRAF1 and activation of the NF-κB pathway." (PMID 30619326, 2018). "These included CD40, TRAF1, EBI3, and ICAM1, which were previously established as TES1 target genes in studies of cell lines overexpressing LMP1, including BL-41 Burkitt and BJAB diffuse large B-cell lymphoma models." (PMID 38009935, 2023).
endothelial dysfunction (2 papers, 2023 to 2025). In vascular diseases, endothelial dysfunction is a systemic pathological state of the endothelium (the inner lining of blood vessels) and can be broadly defined as an imbalance between vasodilating and vasoconstricting substances produced by (or acting on) the endothelium. "It was demonstrated that the genes associated with TNF-α signaling (TRAF1, TNFAIP2, and NFKBIZ) and oxidative stress regulation (SOD2) were significantly upregulated, suggesting that NS1 activates pathways critical for endothelial dysfunction and vascular inflammation." (PMID 40508120, 2025).
Ewing sarcoma (2 papers, 2022 to 2024). A small round cell tumor that lacks morphologic, immunohistochemical, and electron microscopic evidence of neuroectodermal differentiation. "With regard to clinical relevance, MEF3-related genes TRAF1 and TNFSF9, as well as direct cis-targets of DiPRO1 (Dataset EV1A,B) that transcriptionally respond to DiPRO1 KD in RMS and Ewing sarcoma cells in vitro (Dataset EV3), were analyzed in biopsies of recurrent tumors." (PMID 39009887, 2024).
fibrosarcoma (2 papers, 2011 to 2017). A malignant mesenchymal fibroblastic neoplasm affecting the soft tissue and bone. "Cleaved cFLIP then allows a more efficient recruitment of TRAF1/2, the 'receptor-interacting protein' (RIP1) and the the 'rapidly growing fibrosarcoma or rat fibrosarcoma-1' (Raf-1) protein to the cFLIP-caspase-8 heterodimer." (PMID 21477291, 2011).
glioblastoma (2 papers, 2023 to 2024). The most malignant astrocytic tumor (WHO grade IV). "Detailed examination indicated that the highest expressions of TRAF1, TRAF2, TRAF3, TRAF5, and TRAF7 were in Cholangiocarcinoma (CHOL), while TRAF4 was most expressed in Uterine Corpus Endometrial Carcinoma (UCEC) and TRAF6 in Glioblastoma multiforme (GBM)." (PMID 38825674, 2024).
Hepatic steatosis (2 papers, 2021). Steatosis is a term used to denote lipid accumulation within hepatocytes. "Increased TRAF1 expression in the livers of NAFLD patients and TRAF1 overexpression in hepatocytes contributes to the development of insulin resistance, inflammatory response and hepatic steatosis." (PMID 34948191, 2021).